HIF1A (hypoxia inducible factor 1 subunit alpha)
Diseases named in the same sentence as HIF1A in open-access papers (continued):
Sharing a sentence is not in itself a finding about the gene and the disease.
tumor (continued). "Nicotine might function through activating ERK/MAPK signaling pathway, promoting the phosphorylation of ERK protein, and upregulating HIF-1α signaling to promote tumor cell proliferation." (PMID 22952803, 2012). "Interestingly, inhibition of HIF-1α via RNA interference (RNAi) or pharmacological compounds has improved the anti-tumor efficacy in murine cancer models." (PMID 22754381, 2012). "Therefore, YC-1 is expected to become the first antiangiogenic anticancer agent to target HIF-1α, as it was found to halt tumor growth in immunodeficient mice grafted with five types of human tumor cells." (PMID 22736948, 2012). "Thus, the Roc1-Cullin3-KLHL20 complex represents the first PML ubiquitin ligase that is dysregulated in human cancers and the KLHL20-mediated PML destruction and HIF-1α feedback regulation contribute significantly to tumor progression." (PMID 22935031, 2012). "Whether HIF-1α can promote tumor cell apoptosis or anti- apoptosis, the opinion didn't reach unify, different research suggest converse results." (PMID 22453051, 2012). "The hypoxia-induced up-regulation of c-Myc and OCT3/4 in these cells was found to be an HIF-1α-independent event, indicating that such HIF1α-independent mechanisms may also contribute in the tumor angiogenesis." (PMID 23185562, 2012). "FGFs may act in an autocrine manner as the inhibition of FGFR signaling in tumor cells suppresses VEGF-C expression in a COX-2 (cyclooxygenase-2) or HIF1-α (hypoxia-inducible factor-1 α) independent manner." (PMID 22761819, 2012). "Thus, HIF-1α appears to be a key downstream target of miR-21 in the regulation of tumor angiogenesis, even though a putative binding site of miR-21 to 3′ UTR of either HIF-1α or VEGF has been not identified." (PMID 23272057, 2012). "Moreover, forced induction of HIF-1α in HCT 116 cells increases tumor growth and angiogenesis in nude mice." (PMID 22992293, 2012). "Correlation of tumor epidemiological and pathological features with HIF1α expression." (PMID 23028863, 2012). "Hypoxia has been shown to downregulate CAR expression in tumor cells in a HIF-1α dependent manner." (PMID 22720091, 2012). "This might because that the effect of reduced proliferation and increased apoptosis induced by HIF-1α under hypoxia could overcome the effect of enhancing tumor growth by HIF-1α targeted genes in some conditions." (PMID 23762617, 2012). "Our results indicate that the cross-talk between cancer cells and M2-Mφs increased the production of chemoattractants and growth factors, which stimulated the infiltration of blood monocytes into tumor tissues and the proliferation of cancer cells, thereby increasing HIF-1α activation." (PMID 22616919, 2012). "We acknowledge the possibility that HIF-1α may regulate activity of TICs and differentiated cell lineages simultaneously within a tumor." (PMID 22225988, 2012). "Moreover, whereas CDCP1 and HIF-1α expression were reduced in KAI1-expressing tumor tissue, VHL expression was clearly augmented." (PMID 22390300, 2012). "In addition, SIRT3 has been proposed as tumour suppressor via its ability to suppress ROS and regulate HIF-1α thus inhibiting tumour growth." (PMID 22666258, 2012). "The distributions of proliferating cells were analyzed using BrdU staining, in order to examine whether ER-400583-00 acted against HIF-1α-expressing cancer cells in the hypoxic region of U251 tumor xenografts." (PMID 22211243, 2012). "Hypoxia/hypoxia-inducible factor-1α (HIF-1α) regulates many important steps of the metastatic processes, especially epithelial-mesenchymal transition (EMT) that is one of the crucial mechanisms to cause early stage of tumor metastasis." (PMID 23241400, 2012). "HIF-1α expression showed a significant association with tumor grade 2 (p = 0.001), negative PR status (p = 0.013), high MIB1 (p = 0.020) and moderate NPI (p = 0.029)." (PMID 22439624, 2012).
tumor (continued). "Previous reports have shown that inhibition of HIF-1α expression leads to decreased tumor growth." (PMID 22016776, 2011). "The miR-17-92 cluster also modulates tumor growth by inhibiting HIF-1α expression." (PMID 21629773, 2011). "Moreover, the activity of tumor HIF-1a was significantly inhibited by intratumoral administration of SWCNT-HIF-1a siRNA complexes in mice bearing MiaPaCa-2/HRE tumors, suggesting that such SWCNT-siRNA complexes promise considerably as therapeutic agents." (PMID 21995320, 2011). "Also, Immunohistochemistry (IHC) of the tumor sections for expression of P-gp, HIF-1α, EGFR, HXK2, CD-31, and Stem Cell Factor (SCF) was used to assess the MDR character of the tumors after treatment." (PMID 21931642, 2011). "However, the relationship between HIF-1α and NF-κB in the process of tumor development is particularly complex and requires further exploration." (PMID 21887310, 2011). "Sunitinib (SU11248; sutent), an antiangiogenic drug, was effective at inhibiting cellular proliferation and in combination with HIF1 α and enolase siRNA's indicated a synergistic antitumor activity, with a reduction in tumor nodule and tumor microvessel density." (PMID 21754983, 2011). "Inhibiting FIH-1 in CCRCC could be used to bias the HIF response towards HIF-1α and decrease tumour cell viability." (PMID 21386837, 2011). "In addition, it has been thought that over expression of HIF1α and HIF2α is positive related to tumor angiogenesis." (PMID 21812995, 2011). "Furthermore, HIF1α is induced by low oxygen levels and is elevated in fast growing tumours and can activate the inflammatory PTGS-PG system and enhance cellular proliferation." (PMID 21589857, 2011). "We identified that panobinostat/everolimus combination resulted in enhanced anti-tumor activity mediated by decreased tumor growth concurrent with augmentation of p21 and p27 expression and the attenuation of angiogenesis and tumor proliferation via androgen receptor, c-Myc and HIF-1α signaling." (PMID 22087262, 2011). "We also stained tumor sections for endogenous markers of hypoxia, HIF-1α and CA-9." (PMID 21647438, 2011). "Although the detailed mechanism is still undefined, earlier studies have suggested that reactive oxygen species (ROS) and hypoxia-inducible transcription factor 1α (HIF-1α) are potential mediators of cycling hypoxia-mediated tumor progression and radiotherapy resistance." (PMID 21935366, 2011). "Moreover, inhibition of HIF-1α expression alone abolished miR-21-inducing tumor angiogenesis, indicating that HIF-1α is required for miR-21-upregulated angiogenesis." (PMID 21544242, 2011). "The reason for tumor hypoxia is generally believed to result from tumor cell growth outstripping the rate of angiogenesis and consequently, cancer cells react by upregulation of HIF-1α gene and its downstream target genes, including CA IX." (PMID 21535870, 2011). "Thus, our observations are more likely to stem from a delay in tumor initiation due to reduced genomic instability in low oxygen rather than reflect the growth activities known to be stimulated by HIF1-α in established tumor cells." (PMID 21589870, 2011). "In addition we also found that two parameters showed the similar increasing trends along with the growth of transplantation tumor and the time of transduction by HIF-1α." (PMID 21843314, 2011). "TKTL1 may also lead to hypoxic-independent HIF-1α stabilization and the subsequent overexpression of several glycolytic and angiogenic genes, providing a suitable environment for tumor progression." (PMID 21980427, 2011). "ROS and HIF-1α were shown to be the key mediators of tumor angiogenesis, invasion, and metastasis." (PMID 21935366, 2011).
tumor (continued). "In these studies, the researchers found that maximal HIF-1α inhibition and enhanced anti-tumor efficacy is best achieved with Topo 1 inhibitors possessing extended pharmacokinetics, or with a daily low-dose dosing regimen to achieve a higher overall drug level over a longer period of time." (PMID 22081768, 2011). "HIF-1α was expressed in the stem cells forming the GBM tumor spheres." (PMID 21489226, 2011). "Treatment of either CD33+ or CD11b+ tumor-cell line-induced MDSC with lipopolysaccharide, a known activator of MDSC function, caused further up-regulation of STAT3, C/EBPβ, and HIF1α concurrent with increased expression of ARG-1, iNOS, and NOX2-component NCF1 (data not shown)." (PMID 21658270, 2011). "An acidic tumor microenvironment can influence HIF-1α and CAIX expression as well." (PMID 21569415, 2011). "The additional events that are required for tumour development are incompletely understood, but there is evolution from exclusive HIF-1α expression in normal renal epithelium and very early lesions to a predominant or exclusive HIF-2α response in tumours, which is likely to be important." (PMID 21386837, 2011). "SIRT3 is an important tumor suppressor that helps to preserve mitochondrial integrity, inhibits mitochondrial ROS production, and hinders the Warburg effect by suppressing ROS-dependent stabilization of HIF-1α and expression of HIF-1α target genes." (PMID 22072939, 2011). "Consequentially large areas of untreated tumor will stain positive for both HIF-1α and CA-9." (PMID 21647438, 2011). "It has been demonstrated that HIF-1α is more abundant in some tumor cells than in normal cells." (PMID 22346573, 2011). "Moreover, the average tumor growth rate in the HIF-1α gene transduction group was higher than the tumor growth rates in the non-transduction and siHIF-1α groups." (PMID 21843314, 2011). "pFOXO1 and HIF-1α were found to be expressed in both the nuclei and cytoplasm of tumor cells." (PMID 21696576, 2011). "HIF-1α expression is significantly high in adjacent areas of necrosis and tumor infiltration." (PMID 22224081, 2011). "Over expression of HIF1α has been thought to be positively related to tumor progression." (PMID 21812995, 2011). "HIF-1α causes transcriptional activation of several genes, including vascular endothelial growth factor (VEGF) and platelet-derived growth factor (PDGF), both of which are implicated in tumour angiogenesis and growth." (PMID 21285971, 2011). "With regard to SCLC, a common pulmonary solid tumor, angiogenesis regulated by HIF-1α may have an important role in determining tumor phenotypes." (PMID 21843314, 2011). "As mentioned in the sections above, HIF-1α expression induces tumor cell autophagy." (PMID 22190938, 2011). "This dual inhibition may provide additional value in inhibiting angiogenesis and be at least partially effective in inhibiting tumoral HIF-1α surge, tumor invasiveness and metastasis." (PMID 20398289, 2010). "Moreover, we show that u-PAR, VEGFC, and HIF1α, among other targets, are being downregulated, and the tumour-suppressor genes FHIT, RASSF1, and VHL are upregulated upon Enz treatment." (PMID 20736951, 2010). "To identify genetic pathways that might be involved in the reduced migration in vitro, the reduced invasiveness in vivo and the reduced ability to form tumor spheres of cells knocked down for HIF-1α, we performed gene expression profiling analysis." (PMID 20515450, 2010). "As HIF-1α expression is associated with treatment failure and/or patient mortality, targeting HIF-1α could be an attractive treatment strategy, with the potential for disrupting multiple pathways crucial for tumour growth." (PMID 20169098, 2010). "Cells knocked down for HIF-1α formed significantly fewer tumor spheres than control cells." (PMID 20515450, 2010). "Further, we investigated whether targeting HIF-1α affects the hypoxia-induced radioresistance in these tumor cells." (PMID 21050481, 2010).
tumor (continued). "Moreover, only a few studies have been performed to link HIF-1α mRNA expression and tumour-specific parameters." (PMID 20624301, 2010). "The necrotic regions in the OCUM-12 tumours corresponded with HIF-1α or CA9-positive regions." (PMID 20145613, 2010). "This may define a critical role for HIF-2α in the biology of VHL -/- CCRCC enabling greater growth; this demonstrates that in certain contexts HIF-1α can act as a tumor suppressor." (PMID 20652061, 2010). "HIF1β was seen in approximately 80%-100% of HIF1α-positive NE-differentiated tumor cells." (PMID 20663134, 2010). "As HIF-1α is related to poor clinical outcome in some tumours, HIF-1α expression could be used to identify patients who are at risk of developing recurrent disease and who may benefit from adjuvant therapy." (PMID 20565904, 2010). "With regard to the relationship between membranous CAIX and HIF-1α detection, this finding is raising a question on whether and how HIF-1α could influence the CAIX shedding from tumour cell surface." (PMID 20461082, 2010). "Importantly, these cells often become the most aggressive tumour cells, in which CA IX expression is induced by HIF1-α-regulated pathway." (PMID 20398423, 2010). "In these previous studies, sets of genes associated with pathways such as apoptosis (e.g., bax, bcl-2), DNA damage repair (e.g., Ku80, GADD45, XRCC5), cell adhesion (e.g., ICAM-3), angiogenesis (e.g., HIF-1a), and tumor cell invasion (e.g., CTSL, CTSB) were identified." (PMID 20184742, 2010). "The HIF1α-positive cells in FGF8b and mock tumours were seen as hypoxic clusters." (PMID 21034500, 2010). "In addition, the size of the tumor spheres was also significantly reduced in cells knocked down for HIF-1α." (PMID 20515450, 2010). "When oxygen is scarce like in rapidly growing tumours, HIF1α enhances the expression CXCR4." (PMID 20386750, 2010). "HIF-1α activation correlates with metastasis and can promote metastasis through the regulation of key factors governing tumor cell metastatic potential, including E-cadherin, lysyl oxidase (LOX), connective tissue growth factor (CTGF), and plasminogen activator inhibitor-1 (PAI-1), CXCR4." (PMID 20953377, 2010). "Both VEGF and HIF-1α are thought to be crucial mediators of angiogenesis and tumor growth." (PMID 20398289, 2010). "Therefore, zinc can be considered an interesting adjuvant in cancer therapy to target HIF-1α with the potential for disrupting multiple pathways crucial for tumor growth." (PMID 21179202, 2010). "Hypoxia is prevalent in solid tumors and HIF-1α is a critical regulator of tumor hypoxia adaption." (PMID 20932347, 2010). "Interestingly, CXCR4 expression within a tumor increases, through HIF-1α, as the oxygen concentration decreases; this action enhances the metastatic potential of the tumor cells." (PMID 20502531, 2010). "Hypoxia is involved in biological processes promoting tumour progression and stabilises HIF-1α, thereby controlling expression of around a hundred genes involved in tumour metabolism, pH regulation, angiogenesis, migration, and invasion, including the membrane-associated CAIX protein." (PMID 20461082, 2010). "Recently, new evidence indicated that hypoxia may affect the tumor migration process by altering the expression of CXCR4 via activation of HIF-1α." (PMID 20953377, 2010). "We then further asked whether the decrease of miR-20b contributed to a more malignant phenotype of cancer cells, such as the enhanced resistance to apoptosis, the feature of HIF-1α in tumor." (PMID 19893619, 2009). "According to our results, the percentage of perimembranous or diffuse staining pattern turned out to be more important than the intensity and/or percentage of positive tumor cells in relation to HIF-1α or pathological and clinical parameters relevant for disease prognosis." (PMID 19302703, 2009).
tumor (continued). "Clearly more studies are necessary to clarify exactly where CYGB fits in to the cellular hypoxia story and whether it is up- or downstream of HIF1A, currently viewed as the orchestrator of the tumour's response to hypoxia." (PMID 19568272, 2009). "During tumorigenesis, the hypoxic microenvironment and/or genetic alteration pVHL may cause a high level of HIF-1α in cancer cells, suggesting that HIF-1α is a potential target in tumor therapy." (PMID 19893619, 2009). "BRCA1 tumours correlated with positivity for HIF-1α (P=0.008) and negativity for PHD3 (P=0.037)." (PMID 19724277, 2009). "To date, HIF-1α expression in tumour xenografts has been mainly analysed immunohistochemically." (PMID 19223896, 2009). "Because EGFR inhibition can downregulate HIF-1α expression in tumor cells and decrease VEGF secretion, we hypothesized that erlotinib treatment would indirectly lead to vascular normalization and decrease tumor hypoxia." (PMID 19657384, 2009). "Meanwhile, a hypothesis has been deduced from cell culture studies, which proposes loss of an enzymatic function required for HIF1α-degradation as the key mediator of SDH dysfunction, thus, connecting this novel tumor suppressor with the classical VHL gene." (PMID 19949549, 2009). "However, to further increase of HIF-1α and VEGF proteins, tumor cells have to remove the inhibition of miR-20b on HIF-1α and VEGF by downregulating miR-20b." (PMID 19893619, 2009). "However, significant differences in staining procedures and scoring protocols were noted and constitute the most likely explanation for the reported differences in the relative number of HIF-1α-positive tumour cells." (PMID 19223895, 2009). "As expected, the decrease of HIF-1α resulted in the increase of miR-20b in hypoxic tumor cells." (PMID 19893619, 2009). "This may have important treatment implications, as these aggressive tumours may respond to compounds directed against HIF-1α or its downstream targets." (PMID 19724277, 2009). "Moreover, HIF-1α was expressed by 60–75% of the hyperplastic lesions, and a significant association was observed between VEGF and TF in ECs (P<0.005) and invasive tumour cells (P<0.01)." (PMID 19623180, 2009). "Functional inhibition of HIF-1α by means of dominant negative expression constructs or stable siRNA transfection led to significant reduction of neoplastic growth in a broad array of rodent tumour models." (PMID 19223895, 2009). "To determine whether systemic inhibition of these pathways in tumor and host cells provided similar benefit, we used a pharmacologic approach with the HIF-1α inhibitor, 2-methoxyestradiol (2ME2)." (PMID 19727403, 2009). "Taken together, these data suggested that HIF-1α downregulates miR-20b expression in tumor cells." (PMID 19893619, 2009). "The previous studies have showed that HIF-1α is intermediate link in the evolution of the tumor, and this protein could regulate a variety of hypoxia-induced gene expression." (PMID 19245702, 2009). "Translocation of FIH into the cytoplasm may be a mechanism by which BRCA1 and basal-type tumours escape inhibition of HIF-1α activity." (PMID 19724277, 2009). "However, this retardation was rescued by the cotransfection of HIF-1α siRNA, suggesting that miR-20b maintains tumor cell growth through its regulation of HIF-1α." (PMID 19893619, 2009). "In the current study, we measured CYGB gene expression and promoter methylation in a series of head and neck cancer tumours and determined associations with histopathology, clinical characteristics and established markers of tumour hypoxia such as HIF1A expression and tumour thickness." (PMID 19568272, 2009). "In the current study, we have measured CYGB gene expression and promoter methylation in a series of head and neck tumours and determined associations with histopathology, clinical characteristics and established markers of tumour hypoxia such as HIF1A expression and tumour thickness." (PMID 19568272, 2009).